CLDN18 (claudin 18)
Diseases named in the same sentence as CLDN18 in open-access papers (continued):
Sharing a sentence is not in itself a finding about the gene and the disease.
tumor (continued). "Sequential treatment inhibited the growth of the tumor more than those in the FAP + FAP group (p < 0.05), as well as those in the CLDN18.2 + CLDN18.2 group (p < 0.01)." (PMID 37046312, 2023). "Tumor purity, another substantial parameter for the tumor microenvironment, is negatively correlated with CLDN5, CLDN11, and CLDN18 (Absolute value of Spearman Correlation is 0.20 and p < 0.001)." (PMID 37799140, 2023). "ACE2 was homogenously expressed in primary tumor samples from CRC-Liver group, while CLDN18 and DUSP4 were homogenously expressed in Peritoneum samples with a Log2 fold change of −3.267, 4.891 and 2.764 respectively." (PMID 37686695, 2023). "Accordingly, the expression of the target antigen CLDN18 was abolished only in tumors of this group, indicating that H9 CAR-IL15 T cells rapidly and efficiently engaged and killed antigen-positive tumor cells." (PMID 37564658, 2023). "Using the TIMER database, we detected a negative correlation between the mRNA level expression of CLDN5, CLDN8, CLDN11, and CLDN18 and CRC tumor purity." (PMID 35281827, 2022). "In this case, Cldn18 overexpression inhibits insulin growth factor 1 (IGF-1) and YAP/TAZ signaling to reduce p-AKT signaling and suppresses tumor progression." (PMID 35762622, 2022). "In a repetitive in vitro killing assay, CLDN6- or CLDN18.2-TCAR and CAR-BBζ T cells were challenged three times at 5- to 7-day intervals with tumor spheroids derived from CLDN6+ or CLDN18+ PA-1 cells." (PMID 36923303, 2022). "The mean percentage of positive tumor cells for c-MET, RhoA, and CLDN18 expression was 16.2% (SD ± 24, mean H-score = 20.7 ± 36.8), 36.2% (SD ± 30), and 35.0% (SD ± 29.9), respectively." (PMID 35076580, 2021). "Tumor growth inhibitory activity was seen at all ADC doses tested following a single injection and appeared to be dose-dependent in the CLDN18.2-expressing gastric and pancreatic PDX tumor models." (PMID 31182754, 2019). "Taken together, the kinetics of TAC concentrations in the tumor and normal tissues indicate antigen-specific trafficking and accumulation/proliferation of CLDN18.2-TAC T cells to and at its intended target tumor site and corresponds with the kinetics of tumor regression." (PMID 39404622, 2025). "Results were submitted with stained tumor cell percentage and a binary CLDN18.2-positive/negative result for each sample (cut-off: ≥ 75% of tumor cells expressing membranous CLDN18 with ≥ 2+ [moderate to strong] staining intensity)." (PMID 40579565, 2025). "This is an important indication that the CLDN18.2 expression status of the primary tumor or the metastasis alone should not be used as the sole basis for making a treatment decision against zolbetuximab." (PMID 40775258, 2025). "As previously observed in this tumor model, two mice treated with NTD showed varying degrees of TAC-unrelated antitumor responses which, however, was easily distinguishable from the observed CLDN18.2-TAC–specific antitumor response." (PMID 39404622, 2025). "In total, 13.1% (n = 21) of the enrolled patients showed moderate‐to‐strong membranous staining of VENTANA® CLDN18 antibody in more than 75% (75–100%, median = 90%) of the tumour cells while 86.9% (n = 139) were negative." (PMID 39731204, 2025). "This therapy does not have to be targeted only at tumor cells characterized by a high expression of CLDN18.2 but also at those that show moderate and low levels of CLDN18 expression." (PMID 40862764, 2025). "Here, we evaluated the tumor morphology and immunohistochemical expression of CDH17 and CLDN18 in 25 CD-SBNs and potential relationships with gastric differentiation as indicated by MUC5AC and MUC6 immunohistochemistry, wnt pathway mutations, and mismatch repair gene protein immunohistochemistry." (PMID 39164422, 2025). "We first detected the FFA concentrations in the culture supernatants of GC cell lines (MKN45, SNU601, and MFC) and tumor tissues of MFC cell lines with or without CLDN18-ARHGAP fusion (MKN45/SNU601/MFC NC/OE)." (PMID 39164472, 2024).
tumor (continued). "Importantly, NanoBE demonstrated a significant inhibition of tumor growth compared to Nano/CLDN18.2 or Nano/CD40 alone, highlighting the remarkable synergistic effect of nanoengagers through the crosslinking between macrophages and tumor cells." (PMID 38468289, 2024). "Remarkably, unlike Nano/TM and Nano/CD40, DiR-loaded Nano/CLDN18.2 and NanoBE exhibited enhanced tumor accumulation and prolonged retention over time (circle)." (PMID 38468289, 2024). "Quantification analysis of signal intensity from the tumors demonstrated that Nano/CLDN18.2 and NanoBE exhibited significantly higher accumulation compared to Nano/TM and Nano/CD40, highlighting the pivotal role of anti-CLDN18.2 scFv in tumor targeting." (PMID 38468289, 2024). "The results suggest that CLDN18 can be reliably detected in patient tumor samples regardless of the collection method or site using the VENTANA CLDN18 (43-14A) RxDx Assay (for Investigational Use Only; VMSI/Roche)." (PMID 38954176, 2024). "Analysis of the TNMplot database indicated similar expression of METTL7B and RNASE3, downregulation of ITGA9 and SOCS3, and upregulation of CLDN18 in the tumor tissues relative to the adjacent normal tissues." (PMID 37438735, 2023). "Meanwhile, positive CLDN18 expression was not correlated with age, sex, tumor location, lymphatic and perineural invasion, and preoperative CA 19-9 level." (PMID 37629433, 2023). "Nevertheless, we identified CLDN18 overexpression as an independent factor of poor prognosis for HCC, which provides new insights into the pathological mechanism of HCC progression, especially in the context of tumor immune environment." (PMID 37438735, 2023). "In addition, CLDN18 also correlated significantly with markers of activated CD8 + T cells such as MPZL1, CSE1L, CD37, AHSA1, CD3D and IL2RB, after adjusting for tumor purity." (PMID 37438735, 2023). "Studies involving CLDN18 knockout in mice revealed that its deletion leads to tumour formation, even in the absence of Helicobacter pylori infection." (PMID 37582713, 2023). "The expression levels of CLDN18 (P = 4.4e-04) were significantly higher in HCC tissues compared to the normal tissues, whereas METTL7B, ITGA9, SOCS3 and RNASE3 were downregulated in the tumor tissues." (PMID 37438735, 2023). "KATOIII tumor growth was also inhibited by ZL-1211 more potently than benchmark while both antibodies failed to inhibit CLDN18.2-negative SNU5 growth." (PMID 36922936, 2022). "In addition, CAR-T targeting carcinoembryonic antigen (CEA), HER2, CLDN18.2, FOLR1, c-Met, CD133, and CDH17 had a significant anti-tumor effect in the corresponding target-positive GC mouse model and the tumor appeared partially or even complete regression." (PMID 36225938, 2022). "The IHC score reflected strong (3+), intermediate (2+), weak (1+), or lack of membranous staining of CLDN18.2 in tumor cells." (PMID 35642043, 2022). "A total of 324 tumor samples with RNA sequencing data and immune annotation information were included in the study, and their PSI values were all greater than 0.9, which ensured that the main splice isoforms of CLDN18 in these samples were CLDN18.2." (PMID 35811317, 2022). "We analyzed the correlation between CLDN18.2 and other immune checkpoint inhibitors in the tumor core; unfortunately, we did not observe any correlation with PD-1, PD-L1, CTLA-4, LAG-3, or TIM-3." (PMID 35811317, 2022). "Among the 27 cases with two tumor samples available, 18 (66.7%) cases showed concordance in CLDN18 status (13 negative and 5 positive) and 9 were discordant." (PMID 34834447, 2021). "Thus EBV-associated cancers showed the highest prevalence of CLDN18-positive tumours, whereas the GS and MSS/EMT subgroups showed the lowest prevalence in CLDN18-positive status." (PMID 31235864, 2019). "The ADC was tolerated up to 10 mg/kg in rats and the anti-CLDN18.2 diabody did not display obvious signs of toxicity in the stomach of tumor bearing NSG mice 4 weeks following a single dose of 0.34 mg/kg." (PMID 31182754, 2019).
tumor (continued). "In contrast, patients with tumours expressing CLDN18.2 at different levels showed no congruent survival phenotype tendencies, whatsoever (Online Resource 2B)." (PMID 31332522, 2019). "Notably, this study showed that a higher number of CLDN18.2-expressing tumor cells remained in resected specimens in non-MPR cases." (PMID 40749150, 2025). "Therefore, we also confirmed in vivo that inhibiting the PI3K/AKT-mTOR-FAS signaling could specifically trigger anti-tumor effects and downregulate Treg infiltration in the TIME of the GC model with CLDN18-ARHGAP fusion." (PMID 39164472, 2024). "This is an important point because zolbetuximab is administered intravenously and primarily targets peritoneal invasive cancer tissues with blood supply, and therefore information concerning CLDN18 status in the resected PD tissue samples, not just tumor cells floating in ascites, is needed." (PMID 38724721, 2024). "However, Nano/CLDN18.2 did not exhibit enhanced binding affinity to CLDN 18.2-negative tumor cells, indicating that the binding efficiency was mediated by the CLDN18.2 receptors." (PMID 38468289, 2024). "Thus, it is suggested that anti-CLDN18.2-anti-CD28 could play a tumour-killing role by improving antitumour immune response and attenuating the suppressive tumour microenvironment." (PMID 36969060, 2023). "Furthermore, normal HPDE cells receive stimulation to express claudin under certain circumstances, indicating that ectopic activation of claudin-18 is an early effect and PDAC usually has active dominant adherent proliferation and mesenchymal components, while tumor cells are rare." (PMID 36959784, 2023). "In the TCGA study, the CLDN18-ARHGAP26 fusion gene was found to be existed in GS/diffuse GC, and it could promote epithelial-mesenchymal transition and enhance the invasion and metastasis ability of tumor cells, thereby affecting the prognosis of patients." (PMID 37189078, 2023). "However, the survival outcomes were similar regardless of claudin 18.2 positivity when analyzed separately by each tumor stage, and it was not an independent factor for survival outcomes in multivariate analysis as in the metastatic setting." (PMID 37973935, 2023). "In particular, the different expression patterns depending on the region of the tumor indicate that claudin 18.2 expression in endoscopic biopsies may not represent the whole tumor." (PMID 37973935, 2023). "We initially hypothesized that patients with positive CLDN18 expression would have a less aggressive tumor biology than those with negative CLDN18 expression." (PMID 37629433, 2023). "In addition, CLDN18 was significantly overexpressed in HCC tumor tissues compared to adjacent non-tumor tissues, which was consistent with PBMC sequencing results and immunohistochemical data from human protein profiles." (PMID 37438735, 2023). "No case with a CLDN18 2+/3+ staining in between 50% and 74% of tumour cells was identified." (PMID 35925388, 2022). "Thus, we investigated the expression of the tumor markers c-MET, RhoA, and CLDN18 by immunohistochemistry (IHC) in a large and extensively characterized Western cohort of resected GC and its correlation with clinicopathological characteristics and survival outcomes." (PMID 35076580, 2021). "One promising option that has been explored above is AZD0901, an ADC that targets CLDN18.2 to deliver the microtubule-disrupting agent MMAE, thereby directly killing tumor cells without depending on immune system activation." (PMID 41374966, 2025). "Because no additional CLDN18.2-TAC T cells were administered, these results suggest that the second tumor inoculation was rejected by the presence of persisting TAC T cells." (PMID 39404622, 2025). "Interestingly, this meta-analysis did not uncover significant correlations between CLDN18.2 expression and TNM stages, the Lauren classification, HER2 status, or tumor grading." (PMID 38339430, 2024).
tumor (continued). "However, CLDN18.2-TCAR T cells were not as efficient as CLDN18.2-CAR-BBζ T cells, which mediated complete tumor regression in all mice within 4 weeks (middle)." (PMID 36923303, 2022).
cancer (65 papers, 2006 to 2025). A tumor composed of atypical neoplastic, often pleomorphic cells that invade other tissues. "We revealed the association between overall CLDN18.2 expression and OS across ten cancers via Kaplan–Meier analysis." (PMID 39555091, 2024). "Overall, the types of genomic alterations differ between the high- and low-CLDN18.2 expression groups across these cancers, especially the patterns of mutated genes." (PMID 39555091, 2024). "CLDN18 had few mutations in the four cancers, with only a small number of mutations in STAD and CRC, which predominantly consisted of missense mutations and nonsense mutations." (PMID 39555091, 2024). "A pan-cancer analysis of our core target, CLDN18, revealed significant associations with prognosis and immunity across various cancers, confirming its potential for broad application." (PMID 38774870, 2024). "The binding of clones 2, 5, and 9 was also examined using HEK293 + CLDN18.2_M149L, a naturally occurring coding single-nucleotide polymorphism that is present in a small percentage of patients with CLDN18.2-positive cancer." (PMID 39321207, 2024). "Other claudin family members besides CLDN1, CLDN3, CLDN4, CLDN6 and CLDN18.2 have also been implicated in various stages of cancer progression, including metastasis." (PMID 38371623, 2024). "Mechanistically, the loss of CLDN18 promotes the rapid development of cancer cells in the stomach of mice, possibly because CLDN18 is a top regulator and effector of the network that regulates the cytokine, stemness, Wnt and Notch signalling pathways." (PMID 36969060, 2023). "Several cancer cell lines stably expressing CLDN18–ARHGAP26 showed a dramatic loss of the epithelial phenotype and long protrusions showing EMT." (PMID 35053454, 2022). "Because CLDN18 is a tight junction protein, the loss of CLDN18 may induce epithelial-mesenchymal transition and promote cancer cell dissemination into the peritoneal cavity." (PMID 38724721, 2024). "Moreover, we found a significant association between CLDN18 (M) expression and Silva pattern and stromal invasion level (i.e., cancers with Silva pattern C and deep stromal invasion)." (PMID 35861118, 2023). "Thus, CLDN18-ARHGAP fusion is possible a factor for RHOA mutation to maintain cancer cell survival and promoted cell migration." (PMID 36969060, 2023). "Cancer patients show claudin-18 deficiency (both pulmonary and gastric subtypes) early in the Correa cascade, and claudin-18 deficiency is an independent predictor of poor prognosis in cancer patients." (PMID 37582713, 2023). "Similarly, in our study, among primary HPV‐associated ECA samples, 14 (28%) had nuclear positivity, and high nuclear CLDN18 expression was associated with the Silva pattern, with a higher incidence of positive expression in Silva pattern A cancers." (PMID 35861118, 2023). "Among HPV‐associated ECAs, CLDN18 (M) expression levels in intestinal‐type (I‐ECAs) and usual‐type ECAs (U‐ECAs) were significantly different from those in invasive stratified mucin‐producing (iSMILE) carcinomas (p = 0.036)." (PMID 35861118, 2023). "Although Claudin 18 loss may be involved in the carcinogenesis of GC, it was retained in some cancer tissues, but with a range of expression across studies." (PMID 32668412, 2020). "This review has highlighted ongoing and emerging clinical trials that evaluate the efficacy of CLDN18.2-targeted agents in these cancers, which historically lack effective targeted treatments." (PMID 41374966, 2025). "At a population level, transcriptional analyses involving the public Cancer Genome Atlas Program database have found that CLDN18 is downregulated in GC compared to normal gastric tissue, though it is still highly expressed compared to other cancers." (PMID 41374966, 2025). "This review presents a comprehensive synthesis of current advances in CLDN18.2-targeted therapeutics and molecular imaging technologies for cancer management." (PMID 41019366, 2025).